HIPK2 (homeodomain interacting protein kinase 2)
Diseases named in the same sentence as HIPK2 in open-access papers (continued):
Sharing a sentence is not in itself a finding about the gene and the disease.
tumor (continued). "By measuring the mRNA levels of HIPK2-FL and HIPK2-S isoforms in different tumor biopsies and in normal versus tumor tissues, we observed alterations in the relative expression of the two isoforms." (PMID 32093146, 2020). "Most evidence supports HIPK2 as a tumor suppressor, and others suggest HIPK2 as an oncogene and its role in tumor formation/progression appears complex and heterogeneous." (PMID 33043004, 2020). "We observed a large variation in the expression levels of the two HIPK2 isoforms in the different tumor biopsies and in normal versus tumor tissues, indicating tumor-associated variability." (PMID 32093146, 2020). "The serine/threonine kinase HIPK2, which was identified as a potential tumor suppressor in human neoplasms, is involved in transcriptional regulation and apoptosis." (PMID 32641685, 2020). "Homeodomain-interacting protein kinase-2 (HIPK2) has been demonstrated to function as a tumor suppressor in various types of cancer and its overexpression leads to the downregulation of VEGF promoter activity." (PMID 31641356, 2019). "HIPK2 is a potential tumour suppressor, as it promotes apoptosis in response to chemotherapeutic drugs and radiation, mainly by phosphorylating p5327,28." (PMID 30154452, 2018). "Overexpression of p300 promoted the HIPK2-mediated suppression of tumor growth in mouse xenograft model as well." (PMID 29170424, 2017). "We suggest that p300 suppresses the ubiquitination of HIPK2 by acetylation, increasing the protein stability of HIPK2 to enhance the tumor suppressor function under DNA damage conditions." (PMID 29170424, 2017). "As HIPK2 is a tumor suppressor and mediator of DNA damage-induced apoptosis, our results propose a new measure to improve the efficiency of genotoxic cancer therapies by interfering with the HG-induced pathways leading to HIPK2 degradation." (PMID 27901482, 2017). "HIPK2 is a multi-functional signaling molecule and a tumor suppressor that mediates growth, regulation and apoptotic cellular responses." (PMID 28107201, 2017). "Immune-deficient nude mice were injected with HCT116 cells overexpressing p300, HIPK2, or p300 plus HIPK2 and then tumor growth was monitored." (PMID 29170424, 2017). "HIPK2 activation induces Ser422 phosphorylation and degradation of CtBP to repress tumor metastasis." (PMID 28107201, 2017). "Taken together, our data suggest that p300-mediated acetylation of HIPK2 increases the protein stability of HIPK2 and enhances its tumor suppressor function." (PMID 29170424, 2017). "As apoptosis alteration is responsible, among other effects, of tumor resistance to therapies, the regulation of HIPK2 expression level and activity is of particular relevance for the determination of cell fate between survival and death." (PMID 27901482, 2017).
tumor (continued). "Studies have indicated that HIPK2 is involved in tumor invasion by inhibiting various signaling pathways." (PMID 28107201, 2017). "Scientific consensus suggests, HIPK2 is a “caretaker” gene: its inactivation increases tumorigenicity and its activation inhibits tumor growth." (PMID 28107201, 2017). "Homeodomain-interacting protein kinase 2 (HIPK2) is a nuclear serine/threonine kinase that functions in development and tumor suppression." (PMID 29170424, 2017). "Two cases showed both cytoplasmic and nuclear HIPK2 expression in the minority of well-differentiated, dyskeratotic tumor cells." (PMID 28607924, 2017). "Our previous and present studies first demonstrate that the protein stability of HIPK2 and its tumor suppressor function can be regulated by acetylation." (PMID 29170424, 2017). "Previous studies have confirmed that HIPK2 mediates tumor invasion and metastasis, alas with undefined mechanisms." (PMID 28107201, 2017). "HIPK2 can also be activated by DNA damage (i.e. ionizing radiation, UV light), anti-tumor drugs (i.e. cisplatin, adriamycin, roscovitine), zinc in a hypoxic environment, and Traditional Chinese medicine." (PMID 28107201, 2017). "We also confirmed that p300 can potentiate the tumor suppressor function of HIPK2 in the xenograft tumor model in mice." (PMID 29170424, 2017). "We observed that p300 overexpression resulted in both stabilization and enhancement of tumor suppressor function of HIPK2." (PMID 29170424, 2017). "In accordance with the cell culture data, coexpression of p300 and HIPK2 suppressed the tumor growth much more efficiently than each single gene overexpression." (PMID 29170424, 2017). "We were able to confirm the existence of the two alternative splicing forms of Hipk2 in these CSCs as well as in cells from tumor lines or primary normal HUVEC and immortalized HFs." (PMID 26625198, 2016). "We have observed that Wee1 inhibition potentiates Wip1-dependent tumor sensitization effect by reducing levels of Hipk2 kinase, a negative regulator of Wip1 pathway." (PMID 27077811, 2016). "This novel finding is consistent with the function of HIPK2 as a tumor suppressor during pancreatic malignant progression." (PMID 25868975, 2015). "Meanwhile, tumor suppressors HIPK2, HOXA4, and MLL3 were predicted to be similarly targeted by miR-934." (PMID 26472042, 2015). "HIPK2's pleotropic functions include serving as co-regulator of transcription factors, modulator of growth, development, morphogenesis and cell death, tumor suppressor, and regulator of response to DNA damage." (PMID 25972814, 2015). "Altogether, these findings support a new model where HIPK2 acts as a caretaker gene, whose absence causes CIN, which triggers further alterations in the presence of oncogenic stress and ultimately accelerate tumor progression toward a higher malignant state." (PMID 25868975, 2015).
tumor (continued). "Previous studies showed that HIPK2 regulates tumor progression and drug resistance via several potential target genes, such as Bax, p53AIP1, Noxa, etc." (PMID 24846322, 2014). "In this study, we analyzed HIPK2 expression in primary tumor specimens of human CRC, with particular regard to post-operative cancer recurrence, metastasis, and malignancy grades." (PMID 25282590, 2014). "IHC analysis for 100 human CRC tumor samples and 20 normal intestinal tissues, showed HIPK2 expression to inversely correlate with Dukes stage and depth of invasion in CRC (P < 0.05)." (PMID 25282590, 2014). "Homeodomain-interacting protein kinase-2 (HIPK2) is a serine/threonine kinase that as been shown to be involved in tumor suppressor." (PMID 24846322, 2014). "Homeodomain-interacting protein kinase 2 (HIPK2) is a multifunctional protein that exploits its kinase activity to modulate key molecular pathways in cancer to restrain tumor growth and induce response to therapies." (PMID 23144866, 2012). "Homeodomain interacting protein kinase 2 (HIPK2) is a multifunctional kinase whose activity restrains tumor progression." (PMID 23144866, 2012). "This study provides compelling evidence that Hipk2 functions as major tumor suppressor in response to ionising radiation in vivo." (PMID 22889244, 2012). "Other than inducing VEGF expression, HIPK2 knockdown leads to increased prostaglandin E2 (PGE2) biosynthesis that correlates with tumor growth in vivo." (PMID 23144866, 2012). "The role of HIPK2 in restraining tumor development was also confirmed by studies with HIPK2 knockout mice." (PMID 22889244, 2012). "Homeodomain-interacting protein kinase 2 (HIPK2) is a multitalented protein that exploits its kinase activity to modulate key molecular pathways in cancer to restrain tumor growth and induce response to therapies." (PMID 22889244, 2012). "HIPK2 also represses signaling pathways involved in tumor progression, such as Wnt/β-catenin, by means of its catalytic activity and transcription repression function." (PMID 23144866, 2012). "In the present study, we investigated a potential link between E6 from cutaneous HPV types with the tumor suppressor HIPK2." (PMID 22110707, 2011). "Homeodomain-interacting protein kinase 2 (HIPK2) operates as a potential suppressor in skin tumorigenesis and is stabilized by UV-damage." (PMID 22110707, 2011). "We found undetectable or very low levels of HIPK2 protein expression in all tumour samples analyzed." (PMID 21698151, 2011). "Recently, it has been demonstrated that genetic deletion of HIPK2 in mice potentiates skin tumorigenesis induced by the two-stage carcinogenesis protocol, showing that HIPK2 acts as a tumor suppressor in the skin." (PMID 22110707, 2011).
tumor (continued). "We recently reported a novel way to downregulate HIF-1α through transcriptional repression by HIPK2, a potential biomarker for tumor growth." (PMID 21179202, 2010). "HIPK2 is also a transcriptional co-repressor of hypoxia-inducible factor-1α (HIF-1α) restraining tumor angiogenesis and chemoresistance." (PMID 19714248, 2009). "Homeodomain-interacting protein kinase-2 (HIPK2) is a serine/threonine kinase that as been shown to be involved in restraining tumor progression." (PMID 19128456, 2009). "We recently found that HIPK2 co-represses the hypoxia-inducible factor-1α (HIF-1α) transcription factor restraining HIF-1-induced tumor angiogenesis and chemoresistance." (PMID 19714248, 2009). "Specifically, HIPK2 restored the apoptosis-inducing potential of chemotherapeutic drug in hypoxia-mimicking condition and sensitized chemoresistant tumor cells." (PMID 19128456, 2009). "Our studies provide a rationale for the potential use of HIPK2 transduction to sensitize chemosensitive tumor cells to ADR-induced apoptosis." (PMID 19128456, 2009). "We have shown that HIPK2 downregulates the cPLA2-induced prostaglandin E2 (PGE2) production, and that HIPK2 silencing increases in vivo tumor growth and tumor vascularity." (PMID 19128456, 2009). "We present here a potential approach of combining HIPK2 transduction with chemotherapeutic drug for the treatment of chemoresistant tumor cells." (PMID 19128456, 2009). "In addition, more in vivo experiments and analyses of large patient groups, also according to tumor stage and response to therapies, will help to better decipher the prognostic role of HIPK2 and the translational potential in clinical practice." (PMID 39062921, 2024). "To validate this molecular crosstalk in a different tumor type driven by KRAS mutations and to verify whether the HIPK2/KRAS cooperation has a causal role in in vivo tumorigenicity, we chose PDAC, the prototype of oncogenic KRAS-driven cancers." (PMID 39342278, 2024). "Therefore, HIPK2 inhibition in cancer cells can also contribute to tumor progression and resistance to therapies through TME remodeling activities." (PMID 39062921, 2024). "For instance, HIPK2 copy number gain was found to be associated with non-small cell lung cancer (NSCLC) cell lines through activation of the Yes-associated protein (YAP) pathway and subsequently increased tumour proliferation." (PMID 37854071, 2023). "HIPK2 has been extensively studied for its role in restraining tumor progression." (PMID 36831402, 2023). "The role of HIPK2 in restraining tumor angiogenesis has been strengthened by several studies also showing that miRNAs may induce HIPK2 downregulation." (PMID 36900356, 2023). "LINC00261 functions as a tumour suppressor in PC through the miR‐222‐3p/HIPK2/ERK axis." (PMID 34541823, 2021). "HIPK2 has been extensively characterized as a tumor suppressor in kinds of cancers." (PMID 34963484, 2021). "In addition, although some studies demonstrated that miR-1260b can induce angiogenesis via VEGF secretion in tumor cells, our study is the first to show that miR-1260b enhances angiogenesis by targeting HIPK2 in endothelial cells." (PMID 34321461, 2021).
tumor (continued). "Besides, miR-129-5p was found to directly target HIPK2, and suppressed the tumor-like biologic behaviors and inflammation of RA-FLSs via regulating HIPK2." (PMID 33964939, 2021). "Tumor volume monitoring showed that overexpression of HIPK2 significantly inhibited tumor growth." (PMID 33613771, 2021). "HIPK2 is considered a tumor suppressor that modulates growth and apoptotic cellular responses." (PMID 34321461, 2021). "We infer that Drosophila Hipk mimics human HIPK2 in these fibrosis and tumor models." (PMID 29208636, 2018). "HIPK2 is involved in HPV-associated uterine cervical and cutaneous carcinogenesis through its binding of HPV E6, thereby preventing apoptosis and contributing to tumor progression." (PMID 28607924, 2017). "The HIPK2 (serine/threonine homeodomain-interacting protein kinase 2) is a “caretaker” gene, its inactivation increases tumorigenicity while its activation inhibits tumor growth." (PMID 28107201, 2017). "HIPK2 has several well-characterised tumour suppressor roles, but recent studies suggest it can also contribute to tumour progression, although the underlying mechanisms are unknown." (PMID 28692050, 2017). "Additionally, several studies have shown that HIPK2 can also decrease tumor cell invasion and metastasis by Wnt/β-catenin, CTBP, JNK and COX-2 signaling pathways." (PMID 28107201, 2017). "Conversely, restoration of HIPK2 activity in tumor cells is effective for tumor regression." (PMID 28607924, 2017). "To study whether the p300-mediated promotion of HIPK2 function can operate in vivo, we examined the effect of p300 and HIPK2 coexpression in the xenograft tumor model." (PMID 29170424, 2017). "HIPK2 protein was weakly expressed in the nucleus and cytoplasm of the basal layer and was absent in the upper epithelial layers of normal tonsillar surface or crypt mucosa, whereas HIPK2 was diffusely expressed, mainly in the nuclei of tumor cells." (PMID 28607924, 2017). "In this review, we discuss the function of HIPK2 and factors that may increase HIPK2 activity in order to expand current understanding of its anti-tumor effects." (PMID 28107201, 2017). "HIPK2 is now known to be a crucial regulator of DNA damage signaling and tumor suppression." (PMID 27689990, 2016). "Interestingly, the CtBP corepressor protein also co-ordinately regulates cell survival and EMT genetic programs, and is a target of several known tumor suppressors including HIPK2, Ink4a/Arf, and APC." (PMID 27655370, 2016). "However, data are sparse and the HIPK2 role in tumor formation and/or progression is still unclear in a scenario that appears complex and heterogeneous." (PMID 25868975, 2015). "The potential tumor suppressive and neurologic effects of HIPK2 suggest that inhibitors of HIPK2 could have potential adverse effects which need to be carefully watched for in future clinical studies." (PMID 25972814, 2015). "Moreover, we analyzed also the karyotype of human tumor HeLa cells undergoing cytokinesis failure after HIPK2 transient depletion." (PMID 25868975, 2015). "HIPK2 inactivation/dysfunction has been observed in different types of human tumors and several evidences support the notion that the dosage of this tumor suppressor might be relevant." (PMID 25868975, 2015). "One concern of using HIPK2 inhibitors as anti-fibrosis therapy is its tumor suppressive effects." (PMID 25972814, 2015). "In addition to having tumor-suppressive effects, HIPK2 is also needed for TGF-β-mediated survival of midbrain dopaminergic neurons." (PMID 25972814, 2015).